TRIM59-IFT80 (TRIM59-IFT80 readthrough (NMD candidate))
Synonyms: IFT80-L
Gene: Protein-coding gene on chromosome 3 (160,227,454 to 160,449,829, reverse strand). Ensembl gene ENSG00000248710.
Genetic constraint (gnomAD): Missense variants: 821 observed, 908.42 expected, observed/expected ratio (o/e) 0.9, 90% interval 0.85 to 0.96. Synonymous variants: 303 observed, 303.93 expected, observed/expected ratio (o/e) 1, 90% interval 0.91 to 1.1.